RNA5S11 (RNA, 5S ribosomal 11)
Synonyms: RN5S11
Gene: Ribosomal RNA gene on chromosome 1 (228,632,631 to 228,632,749, reverse strand). Ensembl gene ENSG00000199334.
Gene Ontology:
Molecular function: structural constituent of ribosome
Cellular component: ribosome
Homologues: Orthologues: macaque 5S_rRNA (100% identical), rat 5S_rRNA (100% identical). Paralogues in human: RNA5S1 (100% identical), RNA5S10 (100% identical), RNA5S12 (100% identical), RNA5S13 (100% identical), RNA5S14 (100% identical), RNA5S15 (100% identical), RNA5S16 (100% identical), RNA5S17 (100% identical), RNA5S2 (100% identical), RNA5S3 (100% identical), RNA5S4 (100% identical), RNA5S5 (100% identical), and 26 more.